ITGAM (integrin subunit alpha M)
Diseases named in the same sentence as ITGAM in open-access papers (continued):
Sharing a sentence is not in itself a finding about the gene and the disease.
systemic lupus erythematosus (80 papers, 2008 to 2025). An autoimmune multi-organ disease typically associated with vasculopathy and autoantibody production. "Mutations or abnormal expression of the ITGAM gene have been linked to certain autoimmune diseases, including systemic lupus erythematosus and asthma." (PMID 40711007, 2025). "A single-nucleotide polymorphism in the human ITGAM gene, rs1143679, which encodes a loss-of-function mutation (R77H) in Mac-1, is associated with an increased susceptibility to systemic lupus erythematosus, a devastating autoimmune disease in human patients." (PMID 40344054, 2025). "Emerging evidence suggests that variations at the human ITGAM gene encoding the CD11b are strongly associated with susceptibility to systemic lupus erythematosus and lupus nephritis." (PMID 39004752, 2024). "ITGAM, a marker for total macrophages, was considered a risk factor for systemic lupus erythematosus and possibly a protective factor to rheumatoid arthritis." (PMID 35473522, 2023). "Genetic variants in the ITGAM gene are strongly associated with systemic lupus erythematosus (SLE) and its complications (lupus nephritis, etc), as well as with pre-eclampsia." (PMID 37771589, 2023). "The ITGAM gene is a protein-coding gene associated with itGAM-related diseases, including systemic lupus erythematosus and the Shwartzman phenomenon." (PMID 35184762, 2022). "ITGAM, also known as CD11b, was identified as associated with systemic lupus erythematosus and multiple myeloma." (PMID 33860040, 2021). "ITGAM has consistently been associated with susceptibility to systemic lupus erythematosus (SLE) in many ethnically diverse populations." (PMID 31774828, 2019). "More importantly, a GWAS reported that elevated anti-dsDNA autoantibody was strongly associated with ITGAM gene variants in lupus patients, which suggests that functional CD11b is required for suppressing B cells that drive SLE and LN pathogenesis." (PMID 29600248, 2018). "A polymorphism of ITGAM, the CD11b subunit, increases the risk for the autoimmune disease systemic lupus erythematosus (SLE), which shares genetic risk factors with rheumatoid arthritis (RA)." (PMID 29326724, 2017). "The R77H variant of CD11b, encoded by the ITGAM rs1143679 polymorphism, is associated robustly with development of the autoimmune disease systemic lupus erythematosus (SLE) and impairs CR3 function, including its regulatory role on monocyte immune signalling." (PMID 27118513, 2016). "Notably, non-synonymous coding variant of the ITGAM gene is a risk factor to systemic lupus erythematosus (SLE)." (PMID 38468336, 2024). "ITGAM deficiency may enhance disease progression and inflammation in multiple autoimmune models, including lupus." (PMID 35515499, 2022). "Of note, the lupus-associated R77H ITGAM variant lacks this capacity to inhibit FcγR, suggesting regulation of immune complex-mediated leukocyte trafficking could be impaired in individuals with these mutations." (PMID 35634296, 2022). "Interestingly, variations at the ITGAM gene, which encodes for CD11b, is one of the strongest genetic risk factors for systemic lupus erythematosus (SLE)." (PMID 30837997, 2019). "Another pathophysiologic aspect might be related to the rs1143679 (R77H) SNP of the ITGAM (CD11b) gene, that is associated with systemic lupus erythematosus." (PMID 27658051, 2016). "Notably, a number of polymorphisms within or near the gene encoding Integrin alpha M, or ITGAM, have been highly associated with genetic lupus risk factors, with the rs1143679 variant resulting in an R77H substitution in its gene product." (PMID 27846842, 2016). "Genetic variants in the ITGAM gene have been related to systemic lupus erythematosus (SLE) and pre-eclampsia." (PMID 38785556, 2024). "Variants of the ITGAM gene are candidates for genetic susceptibility to systemic lupus erythematosus (SLE)." (PMID 37239465, 2023).
systemic lupus erythematosus (continued). "Accordingly, the mutations in the ITGAM gene (encoding CD11b) are reported as a high-risk factor of developing autoimmune diseases, such as systemic lupus erythematosus (SLE)." (PMID 34971392, 2022). "In patients with systemic lupus erythematosus (SLE), studies have demonstrated the effect of rs114367 single nucleotide polymorphism (SNP) on the level of both the ITGAM transcript and monocyte surface protein." (PMID 34635743, 2021). "ITGAM is associated with the pathogenesis of systemic lupus erythematosus (SLE), and an increasing number of studies have shown a genetic association between ITGAM and various autoimmune diseases." (PMID 33795012, 2021). "The effect of single nucleotide polymorphism (SNP) rs114367 on the level of both the ITGAM transcript and protein on monocytes’ surface in patients with systemic lupus erythematosus (SLE) has been demonstrated." (PMID 33327591, 2020). "Genome-wide association studies (GWAS) have now linked several ITGAM single-nucleotide polymorphisms (SNPs) with the risk and severity of disorders such as systemic lupus erythematosus (SLE), systemic sclerosis, and melanoma." (PMID 31673770, 2019). "Genome-wide association studies (GWAS) have shown that an allelic variant of the alpha-chain, encoded by the ITGAM gene, is associated with risk of developing systemic lupus erythematosus (SLE)." (PMID 23451151, 2013). "Of note, the lupus-susceptibility risk loci PTPRC, NCF1 and ITGAM genes, as well as the IRF8,33–35 emerged as hub network genes, suggesting a pathogenic role during evolution from preclinical to clinical LN." (PMID 35906002, 2022). "Among the KEGG pathways, the top 5 signaling pathways influenced by highly expressed ITGAM were cytokine-cytokine receptor interaction, graft versus host disease, leishmania infection, systemic lupus erythematosus and type I diabetes mellitus." (PMID 36119022, 2022). "FCGR3B, FCGR2A and ITGAM are immune-related genes, all of which are known as biomarkers for systemic lupus erythematosus." (PMID 33602227, 2021). "Numerous previous studies have reported a biological function for ITGAM in the development of systemic lupus erythematosus." (PMID 33104706, 2020). "Moreover, several non-synonymous SNPs localized within ITGAM have been previously associated with systemic lupus erythematosus (SLE) susceptibility." (PMID 31211819, 2019). "In this process, we identified pathways enriched within each signature and found that hub genes correspond to lupus susceptibility risk loci (such as the PTPRC, ITGAM, NCF1 and IRF8 genes), reinforcing their pathogenic role in LN and the progression from preclinical to clinical kidney disease." (PMID 35906002, 2022). "Neutrophil degranulation was the most significantly enriched pathway in this signature, whereas gene network analysis revealed that the lupus-susceptibility risk loci NCF2, ITGAM, NCF1, RASGRP1 and FCGR2A33–35 were high-degree hub genes, suggesting their central pathogenic role in LN." (PMID 35906002, 2022). "Recent genome-wide association studies in lupus patients have identified single nucleotide polymorphisms in or near ITGAM and FCGR2A (the genes for CR3 and Fcγ receptor II, respectively), supporting a potential role for variants of these genes in lupus susceptibility." (PMID 18811944, 2008). "Integrin Subunit Alpha M (ITGAM) encodes the CD11b-subunit of the Mac1 or CD11b/CD18 integrin, which has been repeatedly linked to susceptibility to systemic lupus erythematosus (SLE)." (PMID 37760894, 2023). "ITGAM encodes the α-subunit (known as CD11b) of the β2 integrin (known as Mac1 or CD11b/CD18), which has consistently been associated with susceptibility to systemic lupus erythematosus (SLE)." (PMID 31774828, 2019).
systemic lupus erythematosus (continued). "TLR-stimulated macrophages from ITGAM SNP carriers with systemic lupus erythematosus showed increased basal expression of IRF7 and IFN-β, whereas activation of CD11b inhibited the LPS-induced pro-inflammatory response in macrophages of mice with endotoxic shock." (PMID 36591261, 2022). "Current studies have found that ITGAM is a major non-human leukocyte antigen related to the pathogenesis of autoimmune diseases such as systemic lupus erythematosus (SLE) IgA nephropathy." (PMID 34148032, 2021).
COVID-19 (71 papers, 2020 to 2026). A disease caused by infection with severe acute respiratory syndrome coronavirus 2. "The purpose of this study was to investigate the association between soluble ITGa2, ITGaM and ITGb2 integrin subunits and long COVID-19 pulmonary complications." (PMID 36615143, 2023). "The respective APNet bipartite graph contained a large cluster (IL10RA, ACTN4, ITGB2, IL2RB, BIRC2, ITGAM, HMOX1, TIMP1) linked with established COVID-19 inflammatory and immune signalling cascades." (PMID 39921901, 2025). "The hub protein ITGAM is an essential molecular receptor that plays a vital role in many complements mediated pathways that aggravate the COVID-19 symptoms, such as the C5a-C5aR1 axis in the pathophysiology of acute respiratory distress syndrome." (PMID 37877121, 2023). "Some studies have found that in patients with COVID-19, the expression of ITGAM in females is lower than that in males, indicating that different genders have different mechanisms for regulating inflammation." (PMID 36119022, 2022). "In studies on COVID-19 and Guillain‐Barré syndrome, it was also found that ITGAM is an important factor in the gene regulatory network associated with the two diseases." (PMID 36119022, 2022). "Our analysis also found significant differences in the degree of certain immune cell infiltration and immune checkpoint expression levels between COVID-19 patients with high and low ITGAM expression." (PMID 36119022, 2022). "However, in patients with COVID-19, the expression of ITGAM, vWF, and PLEK was higher when compared with ECs of healthy patients." (PMID 39066212, 2024). "From the sub-module network of hub genes, ITGAM was shown to have the most edges, that is, the most proteins associated with it, so in further studies, the biological role of ITGAM in COVID-19 was focused to explore its potential mechanism in the development and progression of the disease." (PMID 36119022, 2022). "In addition, ITGAM has been identified as one of the crosstalk genes for atherosclerosis and COVID-19 co-morbidity." (PMID 36316672, 2022). "The expression difference analysis indicated that the expression level of ITGAM was significantly different between COVID-19 and normal samples, with p-value < 0.01, suggesting that this signature may have an important role in COVID-19." (PMID 36119022, 2022). "Seven common key genes were found in these four hub gene sets, including FCER1G, ITGAM, LCP2, LILRB2, MNDA, SPI1, and TYROBP, which were considered core targets of IC and COVID-19." (PMID 38267482, 2024). "Studies have found that CD11b can mediate thrombus formation in COVID-19, so ITGAM plays an important role in thrombus formation in COVID-19 patients." (PMID 36119022, 2022). "In this study, we showed that enriched populations of Res-like Mac (HLA-DR+ITGAM−CD68low), M1 Mac (CD68+ITGAM+CCL2+), and pro-inflammatory Mac (CD68+ITGAM−CSF1R−CCL2+) in patients with severe COVID-19." (PMID 34238338, 2021). "Soluble ITGAM and ITGB2 elevation have also been shown to correlate significantly with long-term pulmonary COVID-19 complications and may represent promising biomarkers for predicting such complications." (PMID 38882332, 2024). "Patients with severe COVID-19 had a higher proportion of so-called low density neutrophils within the mononuclear cell fraction, including such immature neutrophil subsets as FUT4 (CD15)+CD63+CD66b+ pro-neutrophils and ITGAM (CD11b)+CD101+ pre-neutrophils." (PMID 35632823, 2022). "Surprisingly, HUVECs incubated with severe COVID-19 serum also showed a decrease in the expression of CCL2, IL6, TNFa, PTGS2, and ITGAM compared with the control that received or did not receive pretreatment with PC." (PMID 39066212, 2024). "Expression of the adhesion molecules ITGAM (integrin alpha M), one subunit of the β-2 integrin CD11b/CD18 or Mac-1, and SELL (L-selectin) is increased in severe, but not mild, COVID-19." (PMID 34108966, 2021).
Obesity (70 papers, 2011 to 2026). Accumulation of substantial excess body fat. "TIRAP, TNFRSF1A, CASP1, CSF1, and ITGAM are associated with the development of type 2 diabetes, a condition linked to obesity." (PMID 39194753, 2024).
viral infection (63 papers, 2005 to 2025). "ITGAM, RUNX1, and PSTPIP2 formed one cluster with high expression in subjects with confirmed bacterial infections, whereas LY6E and IRF-9 formed another cluster with high expression, mainly in patients with confirmed viral infections." (PMID 36900096, 2023). "Interestingly, proteomics directly revealed details on the immune defense against viral infections, including drastic increase in antigen CD177, Integrin alpha‐M (ITGAM) as well as the complex‐forming E3 ubiquitin‐protein ligase DTX3L and PARP9." (PMID 37519267, 2023). "ITGAM, RUNX1, and PSTPIP2 formed one cluster with high expression in subjects with confirmed bacterial infections, whereas LY6E and IRF-9 formed another cluster with high expression in patients with confirmed viral infections." (PMID 36900096, 2023). "Markers of polymorphonuclear myeloid-derived suppressor cells (PMN-MDSCs), CEACAM8 (CD66B) and OLR1 (LOX-1), and markers of monocytic MDSCs (M-MDSCs), IL-4R, ITGAM (CD11B), including a functional marker of MDSCs, ARG1, were positively correlated with the severity of viral infection." (PMID 33765435, 2021).
lung carcinoma (52 papers, 2011 to 2025). "We hypothesized that ITGAM was implicated in the development of MPE by tumor immune response, even though its significance in the PE of lung cancer is yet unknown." (PMID 36684253, 2022). "Despite our literature search, we found that no studies have explored ITGAM’s potential role in lung cancer." (PMID 35291954, 2022).
atherosclerosis (50 papers, 2012 to 2025). A disease characterized by the build-up of fatty material and calcium deposition in the arterial wall resulting in partial or complete occlusion of the arterial lumen. "ITGAM encodes the integrin αM chain that is involved in CD40L-mediated inflammation during atherosclerosis." (PMID 32213192, 2020). "Transcriptome sequencing analysis of ox-LDL-treated endothelial cells showed that ITGAM is a key gene that influences endothelial cell apoptosis and thus promotes atherosclerosis." (PMID 38382092, 2024). "In addition, we revealed for the first time the correlations between ITGB2/ITGAM and various types of immune cells in atherosclerosis plaques by immune cell infiltration analysis." (PMID 35656397, 2022). "Analysis of tissue expression data on porcine atherosclerosis induced by high lipid factors indicates that TYROBP, ITGB2, and ITGAM are key genes influencing the progression of ankylosing spondylitis." (PMID 38382092, 2024). "These six hub genes, TYROBP, ITGAM, ITGB2, CD86, PLEK, LCP2 may be important biomarkers for the progression of atherosclerosis and potential treatment targets." (PMID 38382092, 2024). "This suggests that ITGAM and ITGB2 may play an important role in the occurrence of IPH, immune cell infiltration, and the progression of atherosclerosis." (PMID 35656397, 2022). "In summary, we determined that ITGAM, TYROBP, ICAM1 and CAMP may possess significant roles in mediating the chronic inflammatory process that eventually culminates in atherosclerosis and CAD." (PMID 33758323, 2021). "In this study, we suggested that the progression of atherosclerosis might be related to CD86, C1QB, CD53, C1QC, NCF2, and ITGAM and that it plays a role in regulating immune-competent cells such as T cell CD8 and macrophages M0 and M2." (PMID 32821283, 2020).
asthma (45 papers, 2006 to 2025). "HMOX1, ITGAM, DDX58, SFTPD and ADAM17 were the top novel targets identified for asthma which needs to be validated experimentally." (PMID 37735578, 2023). "We identified HMOX1, ITGAM, SFTPD and ADAM17 as the top novel targets for asthma which need to be validated experimentally whereas IL-18, TNF and VEGFA as the strongest therapeutic targets to investigate further for clinical benefit." (PMID 37735578, 2023). "The levels of most proteins (ITGAM, ITGB2, MMP12, NCF1, NCF2, NCF4, RAC2 and Vav1) were higher in the asthma condition (shown in red) than those in the control condition or after SCIT condition." (PMID 34618857, 2021).
colon carcinoma (45 papers, 2012 to 2025). "CHI3L1, PTPRC, and ITGAM, three key genes in colon cancer proliferation and metastasis, demonstrated the highest baseline expression and significant changes in gene expression." (PMID 38037545, 2023). "ITGAM or CD11b, a marker of macrophage activation, has been shown to be upregulated in colon cancer." (PMID 38037545, 2023).
pancreatic cancer (44 papers, 2013 to 2025). "Led by our mouse data, we stratified pancreatic cancer patients from The Cancer Genome Atlas (TCGA) dataset according to a designed gene list based on classical MDSC markers, including ITGAM (CD11b) and CXCL10." (PMID 31940491, 2020).
Arthritis (43 papers, 2007 to 2025). Inflammation of a joint. "The patient bearing the novel ITGAM variant we identified had a history of proteinuria and pyuria, arthritis but no discoid rash, based on a 5.5 year period of follow up." (PMID 31659207, 2019).
autoimmune disease (39 papers, 2014 to 2025). A disorder resulting from loss of function or tissue destruction of an organ or multiple organs, arising from humoral or cellular immune responses of the individual to their own tissue constituents. "Notably, ITGAM were identified as common genes exhibiting genetic associations among various autoimmune diseases, consistent with the results from the GO functional enrichment analysis." (PMID 39267804, 2024). "Recent reports revealed that NCF2 and ITGAM play significant immune-regulatory roles in autoimmune disease." (PMID 32821283, 2020). "Dysregulation of ITGAM function could lead to impaired immune responses and contribute to the pathogenesis of autoimmune diseases and chronic inflammatory conditions." (PMID 41259376, 2025).
lymphoma (35 papers, 2004 to 2025). A malignant (clonal) proliferation of B- lymphocytes or T- lymphocytes which involves the lymph nodes, bone marrow and/or extranodal sites. "BJAB lymphoma cells express low levels of ITGAL as partner of ITGB2 in LFA-1, and intermediate levels of ITGAM." (PMID 40464949, 2025).
diabetes (33 papers, 2012 to 2026). "Furthermore, numerous studies have shown that ITGAM serves as a hub gene linking PD with various other diseases such as diabetes mellitus type 2." (PMID 41358004, 2025).
breast tumor (32 papers, 2012 to 2025). "While mRNA encoding the myeloid cell marker CD11b (ITGAM) was expressed at equal levels in all breast tumour subgroups, mRNA of the anti-inflammatory markers CD163 and S100A9 were expressed at significantly higher levels in basal than luminal A breast tumours." (PMID 27725631, 2016). "In our analysis of the TCGA breast tumor cohort, we observed significant positive correlations between TREM1 expression and the expression of TREM-1 target cytokines (IL1B, IL8, IL6 and CCL2) and markers of MDSCs and TAMs (CD11B/ITGAM, OLR1, CD14 and CD206/MRC1)." (PMID 34956864, 2021).
colorectal cancer (32 papers, 2013 to 2026). A primary or metastatic malignant neoplasm that affects the colon or rectum. "ITGAM was also linked to implantation metastasis of epithelial ovarian cancer and liver metastasis of primary colorectal cancer, according to other research." (PMID 35291954, 2022). "Lastly, ITGAM encodes CD11b, an integrin which combines with CD18 to form a leukocyte adhesion receptor; bone marrow CD11b+ cells have been shown to promote epithelial-to-mesenchymal transition and metastasis in colorectal cancer." (PMID 32552875, 2020).